MAGEA1 (MAGE family member A1)
Diseases named in the same sentence as MAGEA1 in open-access papers (continued):
Sharing a sentence is not in itself a finding about the gene and the disease.
tumor (85 papers, 2004 to 2026). "Additionally, tumor-associated antigens such as MAGEA1, MAGEA3, and GTAp63 were also induced by Chidamide, promoting antigen presentation and T-cell recognition (data not shown)." (PMID 41049003, 2025). "DAC treatment of tumor cells again resulted in the induction of MAGEA1, MAGEA3/MAGEA6, or MAGEA9 expression as validated by qPCR." (PMID 40791813, 2025). "MAGEA1 expression in healthy cells therefore falls into similar expression range as observed in tumor cells that displayed an expression range between 1% and 100% of HKG." (PMID 40791813, 2025). "Strong anti-tumor reactivity of the CTA-specific TCR T cells against different tumor cell lines correlated with markedly induced expression of MAGEA1, MAGEA3/A6, and MAGEA9 by DAC treatment." (PMID 40791813, 2025). "Target pairs predicted to independently encode for highly tumor-specific antigens (e.g., MAGEA1, MAGEA4, CLDN18) unsurprisingly resulted in highly tumor-specific antigen pairs as well." (PMID 39515334, 2024). "When ranking the tumor specificity of 13,350 genes with protein information in ascending order, targets falling within similar tumor specificity (BayesTS = 0.02) as the well-known targets (e.g., MAGEA1, MS4A1) can be selected for further evaluation." (PMID 39515334, 2024). "As a lowly expressed target in normal tissue and a well-characterized CTAs in solid tumors, the tumor specificity of MAGEA1 shifts from 0.49 to 0.02 and reflects a clear left-skewed distribution for both the tissue distributions and normalized RNA counts." (PMID 39515334, 2024). "The findings also showed that the mRNA expression of CNTN1, ENO1, and MAGEA1 were higher in tumor tissues, whereas the mRNA expression of GATA3 was higher in normal tissues." (PMID 35846128, 2022). "The qRT-PCR results demonstrated that expression of CNTN1, ENO1, and MAGEA1 were higher in tumor tissues, whereas the expression of GATA3 was higher in normal tissues." (PMID 35846128, 2022). "This approach revealed that many MART-1 and some gp100 and MAGEA1 reactive TCR sequences co-clustered with the TCR sequences obtained from the patients’ tumor infiltrates suggesting that the respective cluster is directed against these MDAs/CTAs." (PMID 33275172, 2021). "Individually, MAGEA1, MAGEA3, MAGEA4, MAGEC2 and NY-ESO-1 are highly expressed in HCC and associated with metastasis, tumor recurrence, high AFP levels and poor clinical outcomes." (PMID 34166362, 2021). "Overexpression of the immune MAGEA1 gene, a member of the MAGEA gene family, in tumor and stromal cells is associated with a poor prognosis and an ideal candidate for tumor immunotherapy." (PMID 33431054, 2021). "MAGEA1, a classic CT antigen, is a tumor-specific member of the MAGEA antigen family whose expression has been previously reported in several solid tumors." (PMID 33437521, 2020). "This was consistent with a potential role of histone acetylation in the epigenetic activation of MAGEA1 in tumor cells." (PMID 23472218, 2013). "Higher ICI-4W expression of extracellular matrix (ECM) genes, including trypsinogens (PRSS1 and PRSS2) and matrix metalloproteases, and genes encoding cancer antigens (CTAG2, SAGE1, MAGEA1/A4/A10, POTEE, and PRAME) was significantly associated with ICI resistance and tumor growth during ICI-4W." (PMID 37433281, 2023). "Given that most tumour cells have altered HDAC activities, it is reasonable to postulate that MAGEA1–SKIP-HDAC1 interaction may contribute to transcriptional alterations that favour tumour cell growth by recruiting HDAC1 to these SKIP target genes." (PMID 36980267, 2023). "The first CT antigen, melanoma antigen (MAGE)-1—now known as MAGEA1—was discovered in 1991 using autologous typing, a technique in which tumor cells from a patient are co-cultured with autologous lymphocytes to test for the generation of T cells that target tumor antigens." (PMID 34830845, 2021).
tumor (continued). "Currently, the antigens recognized by T cells in HPVnegVSCC are unknown but the majority of primary VSCC express for instance the well-known tumor antigens MAGEA1 and MAGEA4, but it is unknown if these antigens function as target for the VSCC-infiltrating T-cells as this still needs to be studied." (PMID 31481117, 2019). "In summary, DAC treatment can substantially induce or enhance the reactivity of MAGEA1-, MAGEA3/A6-, and MAGEA9-specific TCR T cells toward diverse tumor cell lines." (PMID 40791813, 2025). "It has been reported that the promoter methylation levels of AKT3, CD147, LINE1, MAGEA1, RASSF1A, and SFRP1 were considerably correlated with OS, tumor volume, and cancer properties." (PMID 38206300, 2024). "In this set, we find that BayesTS ranked the well-established CTAs including MAGEA1 and MAGEA4 as the most tumor-specific targets." (PMID 39515334, 2024). "First, we found multiple MAGE family proteins (e.g., MAGEC2, MAGEB2, MAGEC1, MAGEB6) with a gene expression profile similar to those in clinical trials (MAGEA1, MAGEA4), which have been reported to be tumor specific." (PMID 39515334, 2024). "The examination indicated the hub genes in tumor samples, including GAGE2A, GAGE1, MAGEA9, CTAG1A, CTAG1B, and MAGEA1; and the hub genes in healthy ovarian tissue samples, including SPA17, MAGEC1, KDM5B, SSX4, and MAGEA9." (PMID 37835834, 2023). "In-depth studies into the MAGEA1 gene locus demonstrated that the MAGEA family consists of 12 closely related genes clustered at chromosome band Xq28, of which six are expressed in tumours." (PMID 36980267, 2023). "Known HCC drivers such as LIN28B and candidate driver genes, including a sub-set of CTAs (i.e., MAGEA3, MAGEA1), were significantly upregulated (>10 FC, FDR<0.001) in high grade regions compared to low-grade regions of the same tumor nodule." (PMID 34166362, 2021). "CT47A1, PAGE1, MAGEA9, MAGEC2, and MAGEA1 were detected at protein level in tumor tissues (CT47A1 in 14%, PAGE1 in 23%, MAGEA9 in 11%, MAGEC2 in 59% and MAGEA1 in 34% of tumors)." (PMID 34065388, 2021). "The effects of DAC on MAGEA-1, MAGEA-3, and p16 expressions in blood samples and cell lines are consistent with the results of previous studies of a variety of other tumor types." (PMID 24963497, 2014). "Significant tumor-specific demethylation was found in MAGEA3 (p<0.005), MAGEA12 (p<0.025), MAGEA4 (p<0.018), MAGEA1 (p<0.001), TKTL1 (p<0.025) and MAGEA5 (p<0.007)." (PMID 19997593, 2009). "PRM analysis for peptides from IGFBP3 and MAGEA1 showed probable or definite presence in material from patients without a tumour." (PMID 36185575, 2022). "Enhanced expression of MAGEA-1 and MAGEA-3 on the surfaces of malignant cells might lead to more effective “killing” of the tumor cells by cytotoxic T-cell-receptor-based immunotherapeutics." (PMID 24963497, 2014). "To assess whether MAGE genes were induced to levels that could be relevant for T-cell-mediated recognition, we compared the relative expression levels of MAGEA1, MAGEA3/MAGEA6, and MAGEA9 after DAC induction in healthy cells to the relative expression levels in tumor cells." (PMID 40791813, 2025). "There were 10 lncRNAs that were expressed in more than 20% of the tumor samples (LINC01980, AC025254.1, LINC02806, LINC02476, LINC02506, AL162413.1, LINC00221, LINC01287, AC079466.1, and LINC01419), compared to five protein-coding genes (MAGEA1, MAGEA3, SSX1, DCAF4L2, and MAGEC2)." (PMID 38985879, 2024).
cancer (77 papers, 2006 to 2026). A tumor composed of atypical neoplastic, often pleomorphic cells that invade other tissues. "The two promoter regions displaying cancer hypomethylation (TFF1 and MAGEA1) also displayed an inverse correlation between methylation among cancers and expression indicating that cancer-linked losses in promoter methylation were associated with increased (and abnormal) expression." (PMID 26510686, 2015). "MAGEA1 codes for an antigen that may cause cancer immune suppression." (PMID 36275690, 2022). "By overlapping with TCGA RNA expression profile and pan‐cancer analysis, we found oncogene MAGEA1 was a potential target of MLLT3." (PMID 39716999, 2025). "EDIL3 and DDX43 were the most significantly upregulated genes in patients with high metastatic burden, whereas the cancer-testis (CT) antigens, such as MAGEA1, were found to show reduced expression in these patients." (PMID 32847064, 2020). "MAGEA1, −A4, −A5, −A6, −A8, −A9, − 10 were all expressed at the same level as that of cancer cell lines." (PMID 32760472, 2020). "We found that the promoter regions of TFF1 and MAGEA1 were hypomethylated in cancer compared with adjacent samples (p < 10-5) and in cancer vs. control mammoplasty samples (p < 10-4)." (PMID 26510686, 2015). "Notable exclusions include the cancer/testis antigens MAGEA1, MAGEA3, MAGEA6, GAGE1, GAGE2, GAGE4 and GAGE5, which were originally identified as being strongly upregulated in the PR subgroup but are not upregulated in our PTTG1 high patients." (PMID 26445238, 2015). "MAGEA1 had high mean methylation levels in the control mammoplasty samples and adjacent samples (>80 % for both) but much lower DNA methylation levels in the cancer samples." (PMID 26510686, 2015). "Interestingly, a number of genes encoding CTAs that are potentially useful for developing cancer vaccines were in the list of 63 CTA genes with higher expression levels in the higher-TMB subtype, such as MAGEA (MAGEA-1, 2, 3, 4, 6, 8, 9B, 10, 11, 12), NY-ESO-1, and PRAME." (PMID 30634925, 2019). "Another contributing factor could be the fact that a number of cancer-related genes, known as cancer/testis antigens (CTAs) that are located on the X-chromosome (MAGEA1, SSX1, SSX4, and CTAG1/2), are highly upregulated in PBL, which mainly affect male individuals." (PMID 26108914, 2015). "Regarding vaccines based on specific LC TAAs, besides NY-ESO-1 and MAGEA1 analyses, MAGEA4 has been analyzed as a universal immunoprevention cancer vaccine, and Survivin has been the target of long synthetic peptide." (PMID 39234247, 2024). "Among the most significant genes, a decrease in keratins in HGSIL compared with LGSIL stands out as well as the overexpression of members of the MAGE gene family of cancer/testis antigens in ASCC compared with HGSIL, like MAGEA4, MAGEA3, and MAGEA1." (PMID 39024554, 2024). "CD6, CCL19, CD40LG, XCR1, MAGEA1, ATM and CCL19 genes were significantly differentially expressed in MET-altered cancers." (PMID 33437521, 2020). "Most of the assayed gene regions displayed hypermethylation in cancer vs. adjacent tissue but the TFF1 and MAGEA1 regions were significantly hypomethylated (p ≤0.001)." (PMID 26510686, 2015). "Interestingly, known CTAs, such as MAGEA3, MAGEA1, DSCR8, MAGEC2, and MAGEA6, tended to be identified in the largest number of cancer types." (PMID 39561714, 2024). "Notably in the cancers, there were three groups present: the set around the unity line where MAGEC3 expression was at the limit of detection, a set left of the line (7.1% 23/306) where MAGEA1 is likely expressed, a set right of the line (12.4%, 38/306) where MAGEC3 may be expressed." (PMID 29447163, 2018).
MAGEA1 also shares sentences with these, for which no sentence is quoted: gastric cancer (7 papers); colorectal cancer (4); esophageal squamous cell carcinoma (4); neuroblastoma (4); non-small cell lung carcinoma (4); glioblastoma (3); glioma (3); metastatic melanoma (3); sarcoma (3); acute myeloid leukemia (2); gastric tumour (2); germ cell testicular tumors (2); liver cancer (2); lung adenocarcinoma (2); pancreatic cancer (2); prostate carcinoma (2); renal carcinoma (2); triple-negative breast carcinoma (2); astrocytic tumor (1); bladder tumors (1); chondrosarcoma (1); conjunctival melanomas (1); endometrial carcinoma (1); esophageal cancer (1); Ewing sarcoma (1); female reproductive organ tumors (1); germ cell tumor (1); head and neck squamous cell carcinoma (1); hematologic cancer (1); hematological malignancies (1).
A further 21 diseases each share a sentence with MAGEA1 in 1 paper.